VRK2 (VRK serine/threonine kinase 2)
Diseases named in the same sentence as VRK2 in open-access papers (continued):
Sharing a sentence is not in itself a finding about the gene and the disease.
glioma (4 papers, 2022 to 2026). A benign or malignant brain and spinal cord tumor that arises from glial cells (astrocytes, oligodendrocytes, ependymal cells). "DNA methylation of the VRK2 promoter was associated with low VRK2 expression in human neuroblastomas and adult and pediatric gliomas." (PMID 36040810, 2022). "We observed that in adult glioma high VRK3 expression was correlated with decrease in overall survival independently of the grade of the tumor, whereas VRK2 expression was associated with an increase of survival in high-grade astrocytoma." (PMID 37886173, 2023). "Together, these studies identify VRK1 as a synthetic lethal target in VRK2 promoter–methylated adult and pediatric gliomas and neuroblastomas." (PMID 36040810, 2022). "Taken together, we observed in 3 independent models and cancer lineages that VRK1 depletion leads to tumor repression in vivo, suggesting that VRK1 is a potential therapeutic target in VRK2 promoter–methylated adult and pediatric gliomas and neuroblastomas." (PMID 36040810, 2022). "IDH-mutant gliomas, with their hypermethylated phenotype, also exhibit high VRK2 gene methylation." (PMID 36040810, 2022). "In a separate data set of over 1,000 pediatric high-grade gliomas, including DMGs, we found VRK2 promoter methylation in subsets of histone 3 wild-type and H3 K27M tumors, but VRK2 promoter methylation was most highly associated with the histone H3 G34R mutation." (PMID 36040810, 2022). "It would thus be interesting to investigate if VRK3 depletion is also synthetic lethal in other pediatric tumor entities without hypermethylation of VRK2 promoter, and in particular posterior fossa type A ependymoma and infant high-grade glioma." (PMID 37886173, 2023).
pancreatic cancer (4 papers, 2022 to 2026). "Using pharmacological approaches, we demonstrate that VRK2-deficient pancreatic cancer (PC) cells exhibit heightened vulnerability to glutathione (GSH) metabolic pathway inhibition." (PMID 41856993, 2026). "High VRK2 expression levels are associated with unfavorable prognosis in renal, liver, and pancreatic cancers." (PMID 35911672, 2022). "The findings of this study suggest that VRK2 activates the transcription of NF-κB by phosphorylating IKKβ, thereby promoting the growth of pancreatic cancer cells and enhancing their tumorigenic ability in vivo." (PMID 35173553, 2022). "Our study demonstrated positive correlations between VRK2 expression and tumor size, further suggesting the promoting effects of VRK2 in the progression of pancreatic cancer." (PMID 35173553, 2022). "By analyzing the IHC score of VRK2 in the adjacent tissues and pancreatic cancer tissues, it was found that the protein level of VRK2 was higher in the pancreatic cancer tissues." (PMID 35173553, 2022). "Taken together, these observations suggest that the expression of VRK2 is upregulated in pancreatic cancer and that VRK2 is therefore very likely to play an important role in pancreatic cancer." (PMID 35173553, 2022). "In pancreatic cancer, VRK2 phosphorylates and stabilizes cell cycle kinase Plk1, resulting in Plk1 overexpression to facilitate pancreatic cancer proliferation and chemotherapy resistance." (PMID 35911672, 2022). "First, in this study, the functions of VRK2 in pancreatic cancer were examined using a cell model, and knocking out VRK2 in a pancreatic cancer mouse model would provide more insights into its roles." (PMID 35173553, 2022). "After deletion of the C-terminus, the promotive effect of VRK2 on the colony formation of pancreatic cancer cells was abolished." (PMID 35173553, 2022). "The functions of VRK2 in the progression of pancreatic cancer were examined using CCK8 assay, anchorage-independent assay, EdU assay and tumorigenesis assay." (PMID 35173553, 2022). "The IHC results showed that compared with that in the adjacent tissues, the protein level of VRK2 was increased in the pancreatic cancer tissues." (PMID 35173553, 2022). "It was discovered in this study that the expression of VRK2 was upregulated in pancreatic cancer and that the VRK2 expression level was significantly correlated with the pathological characteristics and the survival time of patients." (PMID 35173553, 2022). "Then, the effect of VRK2 overexpression on the malignant phenotype of pancreatic cancer cells was evaluated." (PMID 35173553, 2022). "This study not only reveals the function and mechanism of VRK2 in pancreatic cancer but also provides a potential therapeutic target for pancreatic cancer." (PMID 35173553, 2022). "These research findings indicate that VRK2 activates the TNFα signaling pathway in pancreatic cancer cells." (PMID 35173553, 2022). "VRK2 promoted the growth, sphere formation and subcutaneous tumorigenesis of pancreatic carcinoma cells as well as the organoid growth derived from the pancreatic cancer mouse model." (PMID 35173553, 2022). "When co-IP was used to test the interaction between endogenously expressed VRK2 and IKKβ in pancreatic cancer cells, endogenously expressed VRK2 and IKKβ were found to form a complex." (PMID 35173553, 2022). "In conclusion, the findings of this study suggest that the expression of VRK2 is upregulated in pancreatic cancer and that VRK2 activates the NF-κB signaling pathway by phosphorylating IKKβ, thereby promoting the progression of pancreatic cancer." (PMID 35173553, 2022).
pancreatic cancer (continued). "In addition, the protein levels of VRK2 in the tumor tissues and adjacent tissues from the same patient were compared, and the results showed that in 81.3% of the patients, there was a higher level of VRK2 protein in the pancreatic cancer tissues." (PMID 35173553, 2022). "This study indicates that VRK2 is likely to be a therapeutic target for pancreatic cancer." (PMID 35173553, 2022). "In addition, in the pancreatic cancer sample, the expression of VRK2 was positively correlated with the phosphorylation level of IKKβ, further indicating the regulatory effect of VRK2 on IKKβ." (PMID 35173553, 2022). "Second, although we have provided evidence that VRK2 activates TNFα/NF-kB signaling in pancreatic cancer cells, when or under what conditions VRK2 controls NF-kB signaling regulation remains largely unknown." (PMID 35173553, 2022). "Currently, the role of VRK2 in pancreatic cancer is poorly understood." (PMID 35173553, 2022). "We found that overexpression of VRK2 in pancreatic cancer cells could activate TNFα/NF-kB pathway, leading to a shift from apoptosis to survival in the circumstance of TNFα." (PMID 35173553, 2022). "Therefore, it is of great importance to target VRK2 in order to inhibit the progression of pancreatic cancer." (PMID 35173553, 2022). "The findings of this study indicate that VRK2 promotes the progression of pancreatic cancer by activating the TNFα/NF-κB signaling pathway, suggesting that VRK2 is a potential therapeutic target for pancreatic cancer." (PMID 35173553, 2022). "Additionally, both the roles of VRK2 in the progression of pancreatic cancer and the related mechanism were investigated." (PMID 35173553, 2022). "Moreover, the protein level of VRK2 in the pancreatic cancer tissues was significantly correlated with pathological parameters, such as tumor size and smoking status." (PMID 35173553, 2022). "In this study, the expression pattern of VRK2 in pancreatic cancer was studied." (PMID 35173553, 2022). "Based on the regulation of PLK1 and IKKβ reported in these two studies, VRK2 might be an important hub of signal transduction in pancreatic cancer." (PMID 35173553, 2022). "Therefore, VRK2 inhibitors might have therapeutic effects on pancreatic cancer by targeting multiple signaling pathways simultaneously." (PMID 35173553, 2022). "The results showed that VRK2 was expressed at low levels in HPDE6C7 cells and at high levels in pancreatic cancer cells." (PMID 35173553, 2022). "Considering hypoxia is one of the hallmarks of cancer 48, it is not strange that VRK2 is overexpressed in the pancreatic cancer." (PMID 35173553, 2022). "The kinase-dead mutant of VRK2 (K61A/K169E) failed to promote the colony formation of pancreatic cancer cells as wild-type VRK2 did." (PMID 35173553, 2022). "Finally, the expression of VRK2 in HPDE6C7 (normal pancreatic cells) and a panel of pancreatic cancer cells was evaluated." (PMID 35173553, 2022).
Fanconi anaemia (3 papers, 2014 to 2015). "Located at 2p16.1, the interval contained genes encoding vaccinia-related kinase 2 (VRK2) and Fanconi anaemia, complementation group L (FANCL)." (PMID 25087078, 2014). "In addition, when analyzing GGE alone, a signal at chromosome 2p16.1 emerged and was narrowed down to the interval containing the genes vaccinia-related kinase 2 (VRK2) and Fanconi anaemia, complementation group L (FANCL); there was no significant signal when evaluating focal epilepsies alone." (PMID 26302787, 2015).
COVID-19 (2 papers, 2023 to 2025). A disease caused by infection with severe acute respiratory syndrome coronavirus 2. "The hypermethylated genes with the lowest p values for hospitalized COVID-19 patients at inclusion (T1) vs. at 6 weeks post-inclusion (T2) were PARP9, ABCA1, MX1, OAS1, ARID5B, and the hypomethylated genes included TMEM131, ROCK1, IFNGR1, CFAP61, VRK2, and C6orf138." (PMID 41227320, 2025).
viral infection (2 papers, 2021 to 2025). "Finally, dSpace analysis identified several genes (CCL2, OASL, CASP7, TMEM123, MAFB, VRK2, UBE2L6, NAPA) higher in patients with mild viral infection than those with severe viral infection or HCs." (PMID 33765435, 2021). "However, during actual viral infection, VRK2 knockdown alone did not affect H5 condensate formation or viral replication, indicating functional redundancy with other kinases such as virus B1." (PMID 41264624, 2025).
anorexia nervosa (1 paper, 2023). A disorder most often seen in adolescent females characterized by a refusal to maintain a minimally normal body weight, an intense fear of gaining weight, a disturbance in body image, and, in postmenarcheal females, the development of amenorrhea. "Of particular interest is the reported link between VRK2 and anorexia nervosa." (PMID 37792698, 2023).
brain tumors (1 paper, 2022). "In brain tumors, lacking VRK1, this compensatory mechanism is impaired by silencing the VRK2 gene, and thus no VRK2 isoform can partially replace VRK1, and cells become more sensitive to DNA damage." (PMID 36011043, 2022).
Cognitive impairment (1 paper, 2026). Abnormal cognition is characterized by deficits in thinking, reasoning, or remembering. "By dissecting this microglia–astrocyte–neuron axis, our findings aim to reveal a novel glial‐mediated mechanism by which VRK2 regulates thalamic circuit function, providing new insight into the cellular basis of attention and cognitive impairments in VRK2‐associated NDDs." (PMID 41263186, 2026).
Ewing sarcoma (1 paper, 2022). A small round cell tumor that lacks morphologic, immunohistochemical, and electron microscopic evidence of neuroectodermal differentiation. "Further, while our data showed a robust connection between VRK2 expression and VRK1 dependency, some tumor lineages, like Ewing sarcoma, demonstrated high VRK2 expression and a strong dependency on VRK1, suggesting that VRK1 may also be required for other tumor cell functions in particular contexts." (PMID 36040810, 2022).
head and neck squamous cell carcinoma (1 paper, 2013). A squamous cell carcinoma that arises from any of the following anatomic sites: lip and oral cavity, nasal cavity, paranasal sinuses, pharynx, larynx, and salivary glands. "The correlation of VRK1 with p63 expression and the correlation of VRK2 with ki67 levels are very consistent with the association of VRK1 and VRK2 with a proliferation phenotype as it had been reported in head and neck squamous cells carcinomas." (PMID 24079673, 2013).
Histiocytosis (1 paper, 2023). An excessive number of histiocytes (tissue macrophages). "The VRK2-ALK and DCTN1-ALK fusion thus may lead to activation of ALK gene driving the tumorigenesis in the ALK-positive histiocytosis." (PMID 36915094, 2023).
Huntington disease (1 paper, 2016). Huntington disease (HD) is a rare neurodegenerative disorder of the central nervous system characterized by unwanted choreatic movements, behavioral and psychiatric disturbances and dementia. "To prove this, alternatively, we investigated VRK2 protein levels in a Huntington’s disease model, R6/2 transgenic mouse, which is a well-studied transgenic animal and most widely used as HD mouse model." (PMID 27377031, 2016).
pancreatic adenocarcinoma (1 paper, 2018). "ADCK1, DAPK3, DMPK STK17A and VRK2 were found to be similarly amplified in other cancers including prostate adenocarcinoma, uterine carcinosarcoma and pancreatic adenocarcinoma." (PMID 29643987, 2018).
rectal cancer (1 paper, 2016). A primary or metastatic malignant neoplasm that affects the rectum. "The impact of the VRK1 and VRK2 kinases in rectal cancer is a novel contribution, providing further insight on the potential role for these kinases in cancer and also representing a new tool for the prediction of response to neoadjuvant treatment in patients with locally advanced rectal cancer." (PMID 27456229, 2016). "This study provides novel data on the role of VRK1 and VRK2 in predicting tumor response to NACRT, and we propose a model with high predictive ability which could have a substantial impact on clinical management of locally advanced rectal cancer." (PMID 27456229, 2016).
renal cell carcinoma (1 paper, 2018). "In renal cell carcinoma cell lines miR-145-5p is dysregulated and several targets, including e2F-associated phosphoprotein (EAPP), Heparan Sulfate 6-O-Sulfotransferase 2 (HS6ST2), Lysyl Oxidase (LOX), Transforming Growth Factor beta-2 (TGFB2) and Vaccinia-related Kinase 2 (VRK2), were confirmed." (PMID 30102719, 2018).
tumor (15 papers, 2013 to 2025). "Collectively, the results confirmed that different amino acid forms of VRK2 were associated with tumor growth and survival rate." (PMID 38186576, 2023). "Increased VRK2 expression levels were positively associated with advanced tumor stage, recurrence, vascular thrombosis, and metastasis." (PMID 37653031, 2023). "Therefore, it is concluded that VRK2, especially dependent on the 167th variant amino acid, can be one of the indexes of tumor progression and proliferation." (PMID 38186576, 2023). "Vrk2 is a serine/threonine kinase that regulates transcription factors in pathways ranging from apoptosis to tumor growth." (PMID 41143948, 2025). "The xenograft tumor model verified that VRK2 knockdown inhibited tumor growth in vivo, accompanied by reductions in both tumor weight and volume." (PMID 41041339, 2025). "Isoleucine-containing VRK2 has higher kinase activity than the valine-containing VRK2, which leads to an increase in tumor cell proliferation." (PMID 38186576, 2023). "By contrast, c.499 = A occurred more frequently in cancer tissues, which indicates that 167I VRK2 is dominant and advantageous for tumor survival." (PMID 38186576, 2023). "The VRK2 gene, primarily expressed in the brain, functions as a mediator of signaling pathways that regulate tumor cell growth and apoptosis." (PMID 37781245, 2023). "In this study, we found that a specific form of 167I VRK2 participates in high tumor proliferation and reduced survival rate." (PMID 38186576, 2023). "We observed that expression of the VRK2A and VRK2B isoforms strongly correlated with each other and that VRK2A represented the majority of total VRK2 transcripts in tumor cell lines." (PMID 36040810, 2022). "The expression of Vrk2 in pancreatic tissues was evaluated, and the results showed that there was a higher level of Vrk2 protein in the tumor tissues." (PMID 35173553, 2022). "In tumor cell enriched regions, SHB, VRK2, KRT6A, GRHPR, CGA, SLC6A8, and LY6D were associated with the survival of NPC patients (P < 0.05)." (PMID 36618352, 2022). "VRK2 regulates tumor cell invasion through the over-activation of NFAT1 and the expression of cyclooxygenase 2 (Vázquez-Cedeira and Lazo, 2012)." (PMID 35559251, 2022). "Since VRK2 plays both a pro-tumor role in malignant cells and an inhibitory role in T cells, it has poignant therapeutic potential in cancer." (PMID 35911672, 2022). "Concerning the expression pattern, VRK1 was detected in the nucleus, while VRK2 was observed mainly in the cytoplasm of tumor cells." (PMID 27456229, 2016). "This manuscript highlights novel data on the role of VRK1 and VRK2 in predicting tumor response to neoadjuvant chemoradiotherapy." (PMID 27456229, 2016). "In conclusion, the proportion of c.499 = A in the mRNA sequence of VRK2 may be utilized as the new tumor growth index." (PMID 38186576, 2023). "We previously suggested that 167I VRK2 increases tumor cell proliferation." (PMID 38186576, 2023). "Taken together, these data indicate that the VRK2-dependent regulation of dysbindin and cyclin D may affect tumor cell proliferation." (PMID 38186576, 2023). "Thus, predicting the tumor growth rate is possible by checking the abundance of various VRK2 transcripts through confirming their RNA sequences at c.499." (PMID 38186576, 2023). "To confirm whether the tumor proliferation through VRK2 is dependent on dysbindin, we performed the CCK8 assay using the dysbindin mutant vector." (PMID 38186576, 2023). "Additionally, in an MC38 murine tumor model, a VRK2 inhibitor AZD-7762 decreased tumor growth in a VRK2-dependent and T cell-dependent manner." (PMID 35911672, 2022). "In addition to its role in tumor progression, VRK2 kinase activity is inhibited by GSK3β in Huntington's disease, thus reducing polyglutamine aggregation." (PMID 35173553, 2022). "In that way VRK2 might contribute to the tumor biological characteristics by modulation of neural cells to growth factors." (PMID 24079673, 2013).
tumor (continued). "Additionally, Ki-67 staining revealed that VRK2 knockdown decreased tumor proliferation." (PMID 41041339, 2025). "Therefore, we investigated that whether VRK2 variants affect tumor cell proliferation, and the results showed that when compared to 167V VRK2, 167I VRK2 reduced dysbindin and increased cyclin D levels, leading to greater tumor cell proliferation." (PMID 38186576, 2023). "However, we noted that VRK2 was still repressed as compared with all other tumor lineages." (PMID 36040810, 2022). "As VRK2 was highly expressed in tumor tissues in all three HCC cohorts in this study, we further investigated the functional role of VRK2 in HCC." (PMID 41041339, 2025). "However, the mechanism behind the role of VRK2 in tumor pathology remains unknown." (PMID 38186576, 2023). "We found that CNS and PNS tumors exhibited the lowest expression of VRK2 across all tumor lineages, while VRK1 expression was slightly reduced in CNS/PNS tumors as compared with all other tumor lineages." (PMID 36040810, 2022). "We evaluated the kinases VRK1 and VRK2, which are known to play multiple roles in cellular proliferation, cell cycle regulation, and carcinogenesis, and as such are potential predictors of tumor response and may aid in identifying patients who could benefit from NACRT." (PMID 27456229, 2016). "Notably, 42% of the 142 methylation‐regulated tumour genes are controlled by multiple methylation sites, especially MGMT (14 sites), AATK (12 sites), VRK2, and FGFR2 (10 sites)." (PMID 41292185, 2025). "VRK2 phosphorylates Ser32 of NFAT1, promoting COX2 transcription and tumor cell infiltration." (PMID 35173553, 2022).